SLCO1B1 (solute carrier organic anion transporter family member 1B1)
Diseases named in the same sentence as SLCO1B1 in open-access papers (continued):
Sharing a sentence is not in itself a finding about the gene and the disease.
Rotor syndrome (16 papers, 2016 to 2026). Rotor syndrome (RT) is a benign, inherited liver disorder characterized by chronic, predominantly conjugated, nonhemolytic hyperbilirubinemia with normal liver histology. "Rotor syndrome is caused by homozygous or compound heterozygous pathogenic variants in both SLCO1B1 and SLCO1B3 genes." (PMID 32082363, 2019). "Here, we report two patients with Rotor syndrome in whom several pathogenic SLCO1B1 and SLCO1B3 variants were identified." (PMID 32082363, 2019). "The Rotor syndrome is caused by bi-allelic mutations in the SLCO1B1 and SLCO1B3 genes." (PMID 38651155, 2024). "At least one wild-type SLCO1B1 or SLCO1B3 allele prevents Rotor syndrome." (PMID 32082363, 2019). "This study provided evidence that the detected genetic mutations in SLCO1B1 and SLCO1B3 are common in Rotor syndrome, which is consistent with previous research." (PMID 40901525, 2025). "Here, for the first time, we report SLCO1B1 and SLCO1B3 gene mutations in Chinese patients with Rotor syndrome." (PMID 32082363, 2019). "Other signals overlapped Mendelian disorder regions, suggesting variable expressivity and broad impact of these loci, as illustrated by signals mapping to Rotor syndrome (SLCO1B1/3), renal cysts and diabetes syndrome (HNF1B), or Charcot-Marie-Tooth (PMP22) loci." (PMID 35240056, 2022). "In addition, 20 patients were diagnosed with a genetic hyperbilirubinemia syndrome: Dubin-Johnson syndrome (ABCC2, n = 17), Rotor syndrome (SLCO1B1/B3, n = 1), Crigler-Najjar syndrome (UGT1A1, n = 1) and Gilbert syndrome (UGTA1, n = 1)." (PMID 35626323, 2022). "Thus, precise identification of SLCO1B1 and SLCO1B3 pathogenic variants by genetic analysis should be used to confirm the diagnosis of Rotor syndrome and to provide guidance for therapeutic drug prescriptions and genetic counseling." (PMID 32082363, 2019). "Pathogenic SLCO1B1 and SLCO1B3 variants identified in patients with Rotor syndrome." (PMID 32082363, 2019). "As Rotor syndrome is a digenic disorder the homozygous LINE-1 insertion alone is not sufficient to cause Rotor syndrome; these patients are also homozygous for a nonsense mutation in the downstream solute carrier organic anion transporter family member 1B1 (SLCO1B1) gene." (PMID 27158268, 2016). "In the current study, we examined SLCO1B1 and SLCO1B3 genes in two Chinese patients diagnosed with Rotor syndrome based on laboratory tests." (PMID 32082363, 2019).
hepatocellular carcinoma (15 papers, 2010 to 2025). A malignant tumor that arises from hepatocytes. "Analysis of the TCGA Liver Hepatocellular Carcinoma dataset (TCGA’s Pan-Cancer Atlas) revealed a low mutation and amplification frequency in HCC for SLCO1B1 (0.57% vs. 0.29%), SLCO1B3 (0.86% vs. 0.29%) and SLCO2B1 (0.57% vs. 0.86%)." (PMID 40734706, 2025). "Analysis of the TCGA Liver Hepatocellular Carcinoma dataset (TCGA’s Pan-Cancer Atlas) revealed a low mutation and amplification frequency in HCC for SLCO1B1 (0.57% vs. 0.29%), SLCO1B3 (0.86% vs. 0.29%), and SLCO2B1 (0.57% vs. 0.86%), respectively." (PMID 40734706, 2025). "The LXRα agonists TO-901317 and GW3965 have been reported to increase the mRNA expression of SLCO1B1 in Huh7 hepatocellular carcinoma cells." (PMID 36839686, 2023). "In hepatoma, HepaRG cells and human hepatocytes, the SLCO1B1, SLCO2B1, SLC22A1 and SLC22A7 expression was down-regulated by an RAR agonist, all-trans retinoic acid." (PMID 36839686, 2023).
Myalgia (15 papers, 2015 to 2025). "In this context, in our study a higher prevalence of myalgia as well as of SASE fear were observed in FH women with SLCO1B1 rs4149056 than men with the same polymorphism or subjects without SLCO1B1 rs4149056." (PMID 38405139, 2024). "Among drug–gene pairs relevant for the cholesterol-lowering drug cohort, for simvastatin-SLCO1B1, a risk of ADRs such as muscle problems including myalgias and rhabdomyolysis was reported in previous studies for the poor metabolism/function phenotype." (PMID 35102241, 2022). "Intriguingly, SLCO1B1 rs4149056 has been recently associated with RVT myotoxicity (a composite of myalgias to rhabdomyolysis) in Han Chinese patients, although it was not previously associated with myalgias in patients of European descent receiving RVT." (PMID 31861911, 2019). "Single nucleotide polymorphisms of the ABCB1 and SLCO1B1 genes have been associated with decreased and increased incidence of myalgia and myositis respectively." (PMID 28771594, 2017). "The prevalence of SASE fear increased from the M/SLCO1B1- group to the W/SLCO1B1+ group and the same was observed in reported myalgia distribution (for both p for trend < 0.01)." (PMID 38405139, 2024). "These SLCO1B1-informed statin therapy switches would avert 109 (95% CI 94 to 141) and 3 (95% CI 2 to 5) SLCO1B1-induced myalgias and myopathies, respectively." (PMID 34834475, 2021). "In the hypothetical cohort, SLCO1B1-informed statin therapy averted 109 myalgias and 3 myopathies at 1-month follow up." (PMID 34834475, 2021). "Concordant with these observations, gene variants of SLCO1B1 and SLCO2B1 were observed with increased frequency in patients with statin-associated myalgia." (PMID 28771594, 2017). "Nevertheless, a genome-wide association study conducted in 2013 with rosuvastatin found no increased risk of myalgia in its users carrying the rs4363657C or rs4149056C alleles in the SLCO1B1 gene." (PMID 40529509, 2025). "The SLCO1B1 *5 allele (rs4149056 C variant) reduces OATP1B1 transport activity, resulting in higher systemic exposure to statins and a significantly increased risk of myotoxicity, including myalgia and rhabdomyolysis." (PMID 41550938, 2025). "The pragmatic SLCO1B1 genotype-informed statin therapy (GIST) trial randomised patients who had discontinued any statins due to myalgia to SLCO1B1 genotype guided therapy (rosuvastatin, pravastatin, or fluvastatin for SLCO1B1*5 carriers and any statin for non-carriers) or standard care." (PMID 38550953, 2023). "For instance, it would be of interest to find out whether patients with a poor or reduced-function SLCO1B1 phenotype required lower doses of atorvastatin or had a higher incidence of myalgias." (PMID 33805706, 2021). "This mechanistic scenario is further bolstered by the discovery that a number of single nucleotide polymorphisms (e.g., SLCO1B1, SLCO2B1 and RYR2) associated with statin myalgia and myositis were observed with increased frequency among patients with statin myalgia." (PMID 28771594, 2017). "In this context, in our study the genetic evaluation of SLCO1B1 rs4149056 presence was able to detect FH subjects who reported myalgia, discontinued high intensity statins and did not achieve the recommended LDL-C target." (PMID 38405139, 2024). "While the frequency of reported statin-associated myalgias is no different than placebo, severe muscle toxicity has been associated with allelic variation in the SLCO1B1 (OATP1B1) gene which facilitates hepatic uptake of the drug." (PMID 34834577, 2021).
cholestasis (13 papers, 2013 to 2025). Impairment of the bile flow caused by obstruction within the liver, or outside the liver in the bile duct system. "In patients with SLCO1B1 variants, which inhibit hepatic uptake of drugs and bile acids, the elevated bile salts are predicted to trigger antimicrobial-induced cholestasis and liver inflammation." (PMID 35754504, 2022). "In the context of DILI, one of the proposed mechanisms of the cholestasis is the competitive inhibition of SLCO1B1 and SLCO1B3 transporters by RIF, thereby impairing hepatic uptake of bilirubin—their endogenous substrate." (PMID 38543282, 2024). "In agreement with previous data which we had described for the hepatic uptake transporters SLC22A1/OCT1 and SLCO1B1/OATP1B1 cholestasis, alcohol consumption, and inflammation determined by C-reactive protein altered SLC10A1/NTCP expression whereas age and gender are of minor importance." (PMID 35806468, 2022).
liver cancer (11 papers, 2011 to 2025). An epithelial or non-epithelial malignant neoplasm that arises from the liver. "SLCO1B1 is overexpressed in colon cancer and a significant relationship between SLCO1B1 expression levels and degree of differentiation in colon and liver cancer has been reported." (PMID 32388639, 2020). "Significant increases were seen for SLCO1B1 in liver cancer [396000 (225000 to 567000) versus 161000 (41000 to 280000); 2.4 fold decrease; P = 0.04]." (PMID 21625523, 2011). "SLCO1B1 expression was lower in liver cancer (P = 0.04) which trended lower with liver cancer grade (P = 0.0004) and higher with colon cancer grade (P = 0.05)." (PMID 21625523, 2011). "However, other notable trends were SLCO2B1 decreased expression by stage in pancreatic cancer, SLCO1B3 increased frequency by stage in prostate cancer, and SLCO1B1 decreased expression by stage in liver cancer." (PMID 21625523, 2011). "Organic anion-transporting polypeptides (OATPs) are upregulated in various solid tumors, including liver cancer, with SLCO2A1 (OATP2A1) elevated in HCC and liver metastases from colon cancer, while SLCO1B1 expression decreases in liver cancer, showing a reverse trend with cancer grade." (PMID 38534987, 2024). "This is the first study indicating that SLCO1B1, SLCO1B1, and SLCO2B1 is significantly expressed (or expression is reduced) in a variety to tumors, including: colon cancer, liver cancer, pancreatic cancer, prostate cancer, testicular cancer, and thyroid cancer." (PMID 21625523, 2011). "Among them, typical liver cancer stem cell markers such as AFP and keratin 19 (KRT19) were upregulated in FOXM1-high HCC, whereas typical mature hepatocyte markers such as solute carrier organic anion transporter family member 1B1 (SLCO1B1) and cytochrome P450 3A4 (CYP3A4) were downregulated." (PMID 35955438, 2022).
acute lymphoblastic leukemia (10 papers, 2013 to 2023). Leukemia with an acute onset, characterized by the presence of lymphoblasts in the bone marrow and the peripheral blood. "SLCO1B1 (1865+4846T>C) was identified in a genome-wide association study as one of the most important factors influencing MTX clearance in patients with acute lymphoblastic leukemia (ALL)." (PMID 37731501, 2023). "Rare damaging variants in the transporter OATP1B1 (SLCO1B1) have been shown to affect methotrexate clearance in children with acute lymphoblastic leukemia." (PMID 37946254, 2023). "A genome-wide association study (GWAS) in patients with acute lymphoblastic leukemia (ALL) showed that genetic variants in SLCO1B1 are associated with MTX clearance." (PMID 32903464, 2020). "SLCO1B1 variants are associated with decreased methotrexate clearance and increased gastrointestinal toxicity for the treatment of acute lymphoblastic leukemia." (PMID 30936830, 2019). "p-values from the association analysis between methotrexate clearence and the SLCO1B1 gene in patients with acute lymphoblastic leukemia." (PMID 25309579, 2014). "Findings of the simulation study were additionally confirmed by a real data set investigating the association between methotrexate clearance and the SLCO1B1 gene in patients with acute lymphoblastic leukemia." (PMID 25309579, 2014). "Certain SLCO1B1 variants associated with enhanced clearance of methotrexate increase the risk of gastrointestinal toxicity when this compound is used to treat children with acute lymphoblastic leukemia." (PMID 27234217, 2016). "Nevertheless, our observation warrants further investigation as SLCO1B1 rs2306283 GG genotype was associated with higher transport activity and lower plasma MTX concentration in children treated for acute lymphoblastic leukemia." (PMID 29422864, 2018). "A recent genome-wide association study among 699 children with acute lymphoblastic leukemia revealed that rs2306283 was associated with increased methotrexate (MTX, also substrates of SLCO1B1) clearance after adjusting for rs4149056." (PMID 24143213, 2013). "Similarly, in acute lymphoblastic leukemia, the SLCO1B1 521T>C SNP reduced methotrexate clearance." (PMID 35456712, 2022). "The importance of both pharmacogenetic and clinical factors has been already shown in leukemia treatment, with SLCO1B1 genetic variability explaining 10.7% and treatment arm explaining ~17% of interpatient variability in MTX clearance among patients with acute lymphoblastic leukemia." (PMID 29422864, 2018).
neutropenia (10 papers, 2011 to 2025). A decrease in the number of neutrophils found in the blood. "Conversely, the SLCO1B1*5 variant (rs4149056) is associated with decreased transporter activity, resulting in higher SN-38 plasma concentrations and an elevated risk of neutropenia, particularly in combination with UGT1A1*28 variant alleles." (PMID 41385496, 2025). "A discovery study on 167 mCRC patients receiving irinotecan also revealed a protective effect of the SLCO1B1 rs2291076 T allele against neutropenia but associated the rs2306283 GG genotype with significantly higher neutropenia events." (PMID 33228198, 2020). "rs2306283 (SLCO1B1*1b) has been shown to cause severe gastrointestinal toxicity, particularly diarrhoea and neutropenia." (PMID 33228198, 2020). "The SLCO1B1*1b variant may serve as a protective biomarker against neutropenia and could enhance efficacy." (PMID 41385496, 2025). "Together, the findings suggest the hypothesis that genetic variants at SLCO1B3 (and/or SLCO1B1) increase the risk of clozapine-associated neutropenia through a pharmacokinetic mechanism." (PMID 27400856, 2017). "This work successfully obtained multiple sets of PBPK model parameters that could reproduce the effects of genetic polymorphisms of UGT1A1 *28 and SLCO1B1 c.521T>C on the plasma concentration of SN-38 and side effects such as neutropenia and diarrhea using a VCS approach." (PMID 28397089, 2017). "In conclusion, UGT1A1*6 and ABCC2 -24C > T polymorphisms may serve as predictors of irinotecan-induced neutropenia, while UGT1A1*6 and SLCO1B1 521T > C are associated with improved progression-free survival in Thai patients." (PMID 41385496, 2025). "UGT1A1*6 and ABCC2 -24C > T variants emerge as potential predictors of irinotecan-induced neutropenia, while UGT1A1*6 and SLCO1B1 521T > C may serve as markers of prolonged PFS in Thai patients." (PMID 41385496, 2025). "Here, we evaluated additional SNPs on the candidate genes: CYP3A4*22, GSTP1, ERCC2, SLCO1B1, and ABCG2, but did not observe a significant relationship with neutropenia and neurotoxicity except for XRCC3 316A>G rs1799794 for GG+AG alleles (p = 0.03)." (PMID 29163177, 2017).
rhabdomyolysis (10 papers, 2012 to 2025). Necrosis or disintegration of skeletal muscle often followed by myoglobinuria. "Sequencing of SLCO1B1, the gene encoding OATP1B1, identified genetic variants associated with a significant reduction in cerivastatin uptake in 122 patients who developed rhabdomyolysis while on cerivastatin." (PMID 37831308, 2023). "Furthermore, statin-induced myopathy and rhabdomyolysis in association with various markers in SLCO1B1 were extensively studied." (PMID 40376268, 2025). "In addition, 17.90% (n = 63) SLCO1B1 (rs4149056, 521TC), 9.09% (n = 32) SLCO1B1 (rs4149056, 521CC) existed in these patients, and patients with these genotypes had a medium and high risk of myopathy and rhabdomyolysis, respectively." (PMID 33731122, 2021). "Only one (rs4149056/c.521C>T in the SLCO1B1 gene) SNP was genomewide significant in the severe myopathy (creatine kinase > 10 × upper limit of normal or rhabdomyolysis) group (P = 2.55 × 10−9; odds ratio 5.15; 95% confidence interval 3.13–8.45)." (PMID 31220337, 2019). "Although the majority of evidence for SLCO1B1-related SRM has been around simvastatin, cerivastatin, a drug that was recalled due to its risk of rhabdomyolysis, has also recently been shown to be effected by this locus." (PMID 25562358, 2012). "The association with the rs4149056 variant in SLCO1B1 was stronger in patients with the severe form of myopathy (CK > 10 × ULN or rhabdomyolysis) irrespective of the statin involved reaching genomewide significance." (PMID 31220337, 2019).
colon cancer (8 papers, 2011 to 2025). "SLCO1B1 was found to be highly expressed in colon cancer, and its expression level was significantly associated with the degree of differentiation in this type of cancer." (PMID 36046013, 2022). "SLCO1B1 was frequently expressed significantly higher with decreasing differentiation in colon tumors (P = 0.04)." (PMID 21625523, 2011). "SLCO1B1 expression levels were significantly related to the degree of differentiation in liver and colon cancers." (PMID 21625523, 2011). "The upregulation of SLCO1B1 induces ferroptosis in colon cancer cells." (PMID 40181576, 2025).
tuberculosis (8 papers, 2012 to 2026). A chronic, recurrent infection caused by the bacterium Mycobacterium tuberculosis. "Furthermore, the polymorphisms of SLCO1B1 were reportedly associated with hepatoxicity caused by drugs, including but not limited to methimazole, methotrexate, atorvastatin and anti-tuberculosis drugs, including rifampin." (PMID 34682349, 2021). "In addition to NAT2, it appears that CYP2E1 and solute carrier organic anion transporter family member 1B1(OATP1B1) coded for by SLCO1B1 gene, could also be important biomarkers for isoniazid-induced liver toxicity in adult patients with tuberculosis." (PMID 26402689, 2015). "Comparisons of CYP2B6, CYP3A5, NAT2, SLCO1B1 and ABCB1 variant alleles and genotype/haplotypes between DILI non-DILI cases among HIV patients with or without tuberculosis." (PMID 22808112, 2012).
diabetes (6 papers, 2016 to 2022). "The frequency of DGI as recently reported for CYP2D6, CYP2C19 and SLCO1B1 further implies that a significant proportion of persons with diabetes will have phenotypes for which actions in principle should be taken regarding dose adjustment or avoidance of the given drugs." (PMID 34577599, 2021). "Thus we hypothesized that the upregulated hepatic Cyp3a and SLCO1B1 by diabetes may increase atorvastatin uptake and metabolism leading to massive ROS formation, which resulted in the enhanced atorvastatin-induced hepatotoxicity in diabetic rats." (PMID 27624558, 2016). "In conclusion, the findings of this study clearly show that a large fraction of persons with diabetes are exposed to drugs or drug combinations for which there exist PGx-based dosing guidelines related to CYP2D6, CYP2C19, and SLCO1B1." (PMID 34577599, 2021). "However, whether SLCO1B1 was also induced by diabetes was not identified." (PMID 27624558, 2016).
coronary heart disease (4 papers, 2021 to 2026). "However, although some of the newly included patients were non-ischemic stroke patients, they were also hospital patients with coronary heart disease rather than healthy controls, so this study could not prove the relationship between SLCO1B1 gene polymorphism and ischemic stroke." (PMID 39944478, 2024).
COVID-19 (4 papers, 2021 to 2025). A disease caused by infection with severe acute respiratory syndrome coronavirus 2. "Variants in CYP3A4, CYP3A5, CYP2C8, CY2D6, ABCB1, ABCC2, and SLCO1B1, among other variants, could be included in pharmacogenetic studies of COVID-19 treatment." (PMID 33807592, 2021). "From the identification of actionable pharmacogenomic markers (such as IFNL3 and SLCO1B1) to the AI-driven proposal of baricitinib as a COVID-19 therapy, we now stand at the threshold of a more systematic, integrative, and evidence-responsive approach to therapeutic innovation." (PMID 41304894, 2025).